RPL13P2 (ribosomal protein L13 pseudogene 2)
Synonyms: dJ599F21.2; RPL13P3; RPL13_7_1707
Gene: Processed pseudogene on chromosome 20 (46,099,518 to 46,100,176, forward strand). Ensembl gene ENSG00000213820.
Diseases named in the same sentence as RPL13P2 in open-access papers:
RPL13P2 is named in the same sentence as 1 disease in open-access papers, as found by Europe PMC text mining. Sharing a sentence is not in itself a finding about the gene and the disease. The quoted sentences say what the papers report.
depression (1 paper, 2023). "The third SNP is the rs2024568 (MTAG-IBS P-value = 1.5E-10) in chromosome 20 (nearest gene was the RPL13P2) previously associated with neuroticism and depression." (PMID 37085903, 2023).